VCAM1 (vascular cell adhesion molecule 1)
Diseases named in the same sentence as VCAM1 in open-access papers (continued):
Sharing a sentence is not in itself a finding about the gene and the disease.
colitis (continued). "In the setting of IBD, the expression of ECAMs like ICAM-1, VCAM-1, and MAdCAM-1 is observed in experimental models of colitis, and also within the inflamed human colon in Crohn's disease and ulcerative colitis." (PMID 15694007, 2005). "In addition to its involvement in inflammatory cell trafficking during colitis and IBD, VCAM-1 has recently been implicated to play a critical role in tumour development in CRC via similar cell migration–based mechanisms." (PMID 40095109, 2025). "Furthermore, the authors demonstrated that the selective inhibition of VCAM-1 with a neutralising monoclonal antibody (mAb) reduced VCAM-1-mediated leukocyte recruitment and significantly attenuated macroscopic colonic tissue damage and colitis symptoms." (PMID 40095109, 2025). "Colitis-associated CRC presents the ideal disease model for observing the potential synergy of the distinct anti-inflammatory and anti-metastatic mechanisms of VCAM-1." (PMID 40095109, 2025). "The promise of alicaforsen as a drug candidate for IBD suggests a similar utility of VCAM-1 ASOs in colitis, which may even be better with the therapeutic blockade of an alternative adhesion molecule." (PMID 40095109, 2025). "The selective blockade of VCAM-1-mediated leukocyte adhesion has, therefore, been suggested as a precise and effective means of inhibiting dysregulated cell infiltration during intestinal inflammation and colitis." (PMID 40095109, 2025). "Another study suggests that VCAM-1 serves as an essential intermediary that sustains and enhances the inflammatory procedure by facilitating the recruitment of leukocytes to the site of inflammatory activity in colitis." (PMID 38601942, 2024). "Furthermore, anti-VCAM1 antibody-coated mesenchymal stromal cells were found to attenuate experimental colitis via immunomodulation." (PMID 37287987, 2023). "The authors of found that DIM suppressed the 2,4,6-trinitrobenzene sulfonic acid (TNBS)-induced colitis in an animal model by reducing ROS generation, as well as diminishing the expression of vascular cell adhesion molecule 1 (VCAM1), which is typically enhanced by ROS." (PMID 36014455, 2022). "VCAM-1 antagonists proved superior to ICAM-1 and MAdCAM-1 blockade in the murine model of DSS colitis, and the monoclonal anti-α4 integrin antibody natalizumab has been successfully used for blockade of VCAM-1-dependent leukocyte trafficking in patients with active CD." (PMID 34017333, 2021). "We believe that the imaging probe of anti-VCAM-1 scFv may also work well in the typical inflammatory lesion of colitis." (PMID 30804723, 2019). "We applied the probe of 99mTc-scFv-VCAM-1 to colitis rabbit to examine its imaging performance." (PMID 30804723, 2019). "However, since monoclonal antibodies directed against other ECAMs, particularly VCAM-1, can as well reduce disease activity in colitis models, the literature suggests that MAdCAM-1 is probably necessary, but insufficient for the maximal penetrance of experimental and probably also clinical IBD." (PMID 16259632, 2005). "However, since monoclonal antibodies directed against other ECAMs, particularly VCAM-1, can as well reduce disease activity in animal models of colitis, the literature suggests that MAdCAM-1 is probably necessary, but insufficient for the maximal penetrance of experimental and clinical IBD." (PMID 15694007, 2005). "We prepared colitis model rabbit with DSS and TNBS, and used the animal for the investigation of 99mTc-scFv-VCAM-1 imaging probe." (PMID 30804723, 2019). "Further, in dextran sulfate sodium-induced colitis mouse models, the neutralization of VCAM-1 by anti-VCAM-1 antibody (MK1.91) disabled leukocyte adhesion to the endothelium and significantly attenuated colitis." (PMID 29614819, 2018).
colitis (continued). "Another study demonstrated that induction of colitis in rats by TNBS is followed by up-regulation of endothelial VCAM-1, and suggests that VCAM-1 and constitutive ICAM-1 are major determinants of leukocyte recruitment to the inflamed intestine." (PMID 22073270, 2011). "The authors found that ICAM-1 and, to a greater degree, VCAM-1 antibody blockade significantly attenuated leukocyte adhesion to colonic venules in experimental rat models of 2,4,6-trinitrobenzene sulphonic acid (TNBS)-induced colitis." (PMID 40095109, 2025). "In contrast to our results, other studies indicate an anti-inflammatory role for 17 HDHA, with negative correlations observed with IL-1β and other cytokines and adhesion molecules such as TNF-α, MIP-2, CXCL1/KC, VCAM-1, ICAM-1, and LFA-1 in an animal model of colitis." (PMID 41009650, 2025). "On the other hand, a relevant report established that VCAM-1 plays a central role in leukocyte recruitment in colitis and blockade of this adhesion molecule has higher therapeutic effect than immune neutralization of ICAM-1 or MAdCAM-1 in colitis experimental model." (PMID 22073270, 2011). "Interestingly, the authors found that simultaneous ICAM-1/VCAM-1 blockade did not further inhibit leukocyte adhesion compared to VCAM-1 blockade alone, implicating VCAM-1 as an optimal adhesion target for selective inhibition of colitis-associated leukocyte recruitment." (PMID 40095109, 2025). "In the same study, chronic administration of anti-VCAM-1 antibody, but not anti-ICAM-1 or anti-MAdCAM-1, resulted in significant attenuation of colitis in terms of disease activity index, colon length, ratio of colon weight to length, and myeloperoxidase activity." (PMID 22073270, 2011).
coronary artery disease (34 papers, 2007 to 2025). "For instance, elevated levels of C-reactive protein, IL-6, ICAM-1, VCAM-1, and E-selectin have been consistently linked to various atherosclerotic manifestations, including peripheral vascular disease, ischemic heart disease, and acute myocardial infarction." (PMID 39851572, 2025). "Higher levels of plasma intercellular adhesion molecule-1 (ICAM-1), vascular cell adhesion molecule-1 (VCAM-1), and E-selectin in community-dwelling subjects and in coronary arterial disease patients are associated with C. pneumoniae seropositivity." (PMID 24376840, 2013). "Basic experimental and clinical data have indicated that higher levels of VCAM-1 in serum or tissue are associated with coronary artery disease, ischemic cardiomyopathy, acute myocarditis, and atrial fibrillation (AF); thus, VCAM-1 represents a potential biomarker for CVDs." (PMID 35222039, 2022). "Furthermore, considering the association of preoperative levels with clinical outcome, VCAM1 has been suggested as a predictive biomarker for heart failure-related mortality and morbidity, endothelial injury in coronary artery disease and arrhythmias such as atrial fibrillation." (PMID 38379859, 2023). "The sVCAM-1 levels in patients with atrial fibrillation, ischemic cardiomyopathy, coronary artery disease, and acute myocarditis are elevated, and both VCAM-1 and sVCAM-1 are regarded as biomarkers of autoimmune myocarditis, cancer, and immunological diseases." (PMID 40070829, 2025). "Intracellular cell-adhesion molecule-1 (ICAM-1) and vascular cell adhesion molecule-1 (VCAM-1) are expressed on the surface of endothelial cells which can be a biomarker for the prediction of coronary artery diseases." (PMID 31491986, 2019). "In one study, this adipocyte-derived secretory protein inhibited TNFα-induced expression of ICAM-1 and VCAM-1, and its circulating levels were lower in patients with coronary disease." (PMID 27459718, 2016). "Evidences support a crucial role for C. pneumoniae seropositivity, as it associated with a higher level of plasma ICAM-1 and VCAM-1 in the general population and a higher level of plasma ICAM-1 and E-selectin in coronary arterial disease patients." (PMID 22900050, 2012). "Notably, adhesion molecules like ICAM-1 and VCAM-1 have shown promise in predicting the onset of coronary heart disease." (PMID 39851572, 2025). "The previous literature showed that consumption of high fat diet caused deposition of inflammatory cells, lipid infiltration and localization of Intercellular Adhesion Molecule-1 (ICAM-1) and Vascular Cell Adhesion Molecule-1 (VCAM-1) that are key indicators of coronary heart diseases." (PMID 36276841, 2022). "As one of the highest incidences of CVDs, coronary artery disease links with more than 20 targets in this T-cD network, such as VCAM1 and ICAM1 (reported to increase in dysfunctional endothelial cells), MMP9, MMP3, and MMP2 (being influencing factors in cardiac fibrosis)." (PMID 29861771, 2018). "In fact, C. pneumoniae infection induced cytokines, E-selectin, ICAM-1, and VCAM-1 expression in endothelial cells; the patients suffering from coronary artery disease had a higher plasma level of ICAM-1 and E-selectin, which was associated with Chlamydia IgA LPS seropositivity." (PMID 22900050, 2012). "The expression of VCAM-1 has been proposed as a biomarker in immunological diseases (experimental autoimmune myocarditis), as a predictor of mortality and morbidity in patients with chronic heart failure, and in those with endothelial injury in patients with coronary artery disease and arrhythmia." (PMID 40623042, 2025). "Associations between VCAM-1 levels and 2-day average black carbon (BC) exposures have also been reported, as well as between longer BC exposure averages (4–12 weeks) and ICAM-1, and lastly 1–2 day lagged associations between EC and ICAM-1 in coronary heart disease patients." (PMID 24314116, 2013).
coronary artery disease (continued). "Four clinical studies were eligible.According to Tavakoli-Rouzbehani et al25 reported that 2 g/day N. sativa oil for 8 weeks considerably decreased serum VCAM-1 and ICAM-1 in coronary artery disease patients compared with the control patients." (PMID 40365513, 2025). "A single LDL apheresis session was able to significantly reduce E-selectin, VCAM-1 and ICAM-1 levels in patients with coronary arterial disease." (PMID 38398435, 2024). "It has been reported that the consumption of a high-fat diet (HFD) caused deposition of inflammatory cells, lipid infiltration and localization of Intercellular Adhesion Molecule-1 (ICAM-1) and Vascular Cell Adhesion Molecule-1 (VCAM-1), which are key indicators of coronary heart diseases." (PMID 36276841, 2022). "ICAM-1 and E-selectin (but not vascular cell adhesion molecule 1) have also been shown to predict carotid artery atherosclerosis and development of coronary heart disease." (PMID 28051279, 2016). "Our results demonstrated that the plasma Gas6 levels were significantly lower in advanced coronary artery disease patients undergoing CABG than in control subjects and that plasma Gas6 levels were negatively correlated with fasting glucose, E-selectin, and VCAM-1 levels." (PMID 24236135, 2013). "The aim was to determine if endothelial VCAM-1 (eVCAM-1) expression in the common carotid artery (CCA) would correlate with predictive markers of atherosclerotic disease, would precede reduction of markers of endothelial cell function and would predict coronary artery disease (CAD)." (PMID 26702331, 2015). "Previous studies showed that aged garlic increased flow-mediated endothelium-dependent dilation (FMD) in men with coronary artery disease (CAD) after a 2-wk treatment, with no significant changes in VCAM-1 levels and lipid profile." (PMID 37513556, 2023). "Another study indicated that intramuscular administration 300000 IU vitamin D supplement in type 2 diabetes (T2D) patients with ischemic heart disease had no significant changes in the levels of ICAM-1 and VCAM-1." (PMID 33224249, 2020).
glioma (34 papers, 2009 to 2026). A benign or malignant brain and spinal cord tumor that arises from glial cells (astrocytes, oligodendrocytes, ependymal cells). "In parallel, glioma-associated macrophages are stimulated by glioma cells to produce tumor necrosis factor-α (TNFα), which activates the endothelial cell expression of the proangiogenic molecules (VCAM-1, ICAM-1, CXCL5, and CXCL10)." (PMID 35740307, 2022). "Vascular cell adhesion molecule-1 (VCAM-1) is an important cell surface adhesion molecule associated with malignancy of gliomas." (PMID 23593320, 2013). "Glioma-associated upregulation of VCAM-1 in endothelial cells may further increase MCNP permeability under pathological conditions." (PMID 40624508, 2025). "Notably, glioma cells have also been implicated in the upregulation of VCAM-1 on endothelial cells, further increasing MCNP permeability under pathological conditions." (PMID 40624508, 2025). "Using syngeneic and primary mouse glioma models, we characterized VCAM1 expression in tumor and stromal cell populations." (PMID 42109665, 2026). "Crucially, the selective deletion of astrocytic VCAM1 significantly extended the median survival of glioma-bearing mice, such as from 52 to 66.5 days in a hippocampal GL261 model." (PMID 42109665, 2026). "To determine if VCAM-1+ cells were present in the context of glioma, we collected brain tissue from mice with established intracranial CT2AvIII glioma or sham controls." (PMID 40244705, 2025). "We also report here increasing lymphocyte VLA-4 expression and increasing numbers of VCAM-1+ endothelial cells/pericytes in the context of glioma over the course of tumor progression." (PMID 40244705, 2025). "This was achieved due to the presence of VCAM-1 in bEnd.3 and glioma cells, which can combine with certain integrins such as α4 and β1, expressed on the surface of macrophages." (PMID 39911305, 2025). "Intratumoral lymphocytic VLA-4 and endothelial/pericytic VCAM-1 expression increase over time in glioma." (PMID 40244705, 2025). "In particular, VCAM-1 expression is up-regulated in the higher grade of clinical gliomas, human primary breast tumors and human colorectal cancer tissues." (PMID 36497180, 2022). "In fact, we show that high expression of VCAM1 correlates with worse survival outcome in IDH-wt glioma patients." (PMID 33853689, 2021). "The miR-181 family regulates VCAM-1 expression, and a low level of miR-181b is observed in high-grade glioma patients." (PMID 34113619, 2021). "Our previous study revealed that higher levels of VCAM-1 correlated with poor prognosis in glioma patients." (PMID 29301329, 2018). "Instead, we find that cytokine stimulation induces VCAM-1 expression by glioma cells, an observation of potential significance for understanding cytokine influences on glioma progression and dissemination." (PMID 24787244, 2014). "VCAM-1 expression emerges late in tumorigenesis and is positively correlated with malignancy grades in various tumors including glioma." (PMID 24787244, 2014). "As an adhesion molecule, induction of VCAM-1 on glioma cells by inflammatory cytokines is of potential clinical significance." (PMID 24787244, 2014). "Our data suggest IFN-β increased ICAM1 and VCAM1 directly or indirectly through inhibition of VEGF production with glioma cells, resulting reversal of leukocyte adhesion." (PMID 25175315, 2014). "U87 human glioma cells were treated with artemether at various concentrations and shRNA interfering technology was employed to silence the expression of VCAM-1." (PMID 23593320, 2013). "Studies have revealed that PI3K/Akt signaling pathway is activated in the invasion of gliomas and is involved in the regulation of VCAM-1 and MMP-2/9 expressions." (PMID 23593320, 2013). "Based on these results, we further investigated the role of VCAM-1 in the malignant behavior of glioma cells with RNA interfering silence technology." (PMID 23593320, 2013).
glioma (continued). "In this work, we investigated the role and mechanism of artemether combined with shRNA interference of VCAM-1 (shRNA-VCAM-1) on the migration, invasion and apoptosis of glioma cells." (PMID 23593320, 2013). "VCAM-1 is also the key factor in the glioma induced bone marrow stromal stem cell (BMSCs) migration." (PMID 23593320, 2013). "Nevertheless, the applications of artemether and anti-VCAM-1 in glioma therapy and detailed molecular mechanisms merit further studies." (PMID 23593320, 2013). "The application of anti-VCAM-1 antibody significantly inhibited the growth of the glioma transplanted into rats and prolong the survival of tumor bearing rats." (PMID 23593320, 2013). "Next, the role of VCAM-1 in the migration and invasiveness of human glioma cells was investigated with shRNA-VCAM-1 U87 cells." (PMID 23593320, 2013). "Two angiogenesis related genes, well-known in glioma biology, VCAM1 and VEGF, were overexpressed in Patient 2 reflecting the high degree of neovascularization." (PMID 19830138, 2009). "One plausible mechanism involves the contact between integrin α4/β1/αvβ3, Macrophage-1 antigen (Mac-1), and CC-chemokine ligand 2 (CCL2) present on the cell membranes of macrophages and vascular cell adhesion molecule-1 (VCAM-1) present on the cell membranes of BVECs and glioma cells." (PMID 39911305, 2025). "Moreover, we observed also an increasing level of ICAM-1 and VCAM-1, strongly related to glioma clinico-pathological grade." (PMID 41029387, 2025). "Additionally, VCAM-1 is overexpressed on glioma cells, enhancing MCNP binding and tumor-targeting capabilities." (PMID 40624508, 2025). "Due to its functions and the high expression of VCAM-1 in glioma, targeting this molecule may be a strategy to increase the effectiveness of the therapy." (PMID 39201395, 2024). "It has been shown that PDT can induce an increase in the VCAM-1 levels in glioma." (PMID 39201395, 2024). "We found that decreasing the expression level of GNG5 in glioma cells could significantly affect the expression of VCAM1, ICAM1, CDH2, and SDC2, which are key molecules of cell adhesion molecules." (PMID 34098960, 2021). "Furthermore, TMEM140 knockdown remarkably decreased the protein levels of ICAM1, VCAM1, and Syndecan1, which are considered to be important in glioma cell migration and invasion." (PMID 26198430, 2015). "While this work calls into question previous studies that have used the B-D13 antibody to assess IL13Rα2 expression, it also suggests that TNF may have significant effects on glioma biology by up-regulating VCAM-1." (PMID 24787244, 2014). "Since CXCR7 knockdown significantly suppressed HBMEC adhesion to matrigel and glioma cell lines, we questioned whether this could be due to a coordinate change in VCAM-1 levels." (PMID 25084358, 2014). "Glioma tissues express higher level of VCAM-1 compared with normal brain tissue." (PMID 23593320, 2013). "It has been reported that VCAM-1 is highly expressed in the glioma tissues." (PMID 23593320, 2013). "Vascular cell adhesion molecule-1 (VCAM-1) is one of the important cell surface adhesion molecules expressed by gliomas and its expression is positively correlated with the malignancy grades, suggesting that VCAM-1 expression is a relatively late phenomenon in tumorigenesis." (PMID 23593320, 2013). "Furthermore, ICAM-1 and VCAM-1 play important roles in the adhesion of cancer cells to the endothelium, especially in the context of the inflammatory microenvironment, supported by the high concentration of IL-1b, correlated with higher grade gliomas." (PMID 35741603, 2022). "Moreover, the VCAM-1 levels positive correlated with the glioma pathological grade." (PMID 31207928, 2019). "In addition, studies also showed that anti-VCAM-1 antibody could significantly inhibit the growth of the glioma and prolong the survival of tumor bearing rats." (PMID 23593320, 2013).